CD4 (CD4 molecule)
Diseases named in the same sentence as CD4 in open-access papers (continued):
Sharing a sentence is not in itself a finding about the gene and the disease.
emphysema (continued). "Also, there was a significant association among decreased CD46+ cells with decreased CD4+T cells, apoptosis mediator CD95 and increased CD8+T cells that were protecting patients without emphysema or severe chronic obstructive pulmonary disease." (PMID 21573156, 2011). "Moreover, chronic cigarette smoke can induce an adaptive immune response, including CD4+ T cells, cytolytic CD8+ T cells, and B cells, leading to cellular necrosis and apoptosis, immune and complement deposition, tissue injury with airway remodeling, and emphysema." (PMID 28536707, 2017). "Given the cross-sectional nature of the study, we cannot determine whether the low CD4/CD8 ratio is contributing to emphysema pathogenesis or whether emphysema drives a low CD4/CD8, as the CD4/CD8 ratio could be depressed in the setting of local inflammation and tissue destruction from emphysema." (PMID 28122034, 2017). "CD4+ T cells polarized to TH1 and TH17 phenotypes have been identified in the lungs of emphysema patients, but not in lungs of control subjects." (PMID 24805101, 2014). "The expression of TLRs on lung CD4+ T cells and NKT cells did not correlate with percent emphysema, implying that the regulation of TLRs within the lung environment in a given patient differs between lymphocyte subsets." (PMID 23374856, 2013). "Notably, the knockout of HAVCR2 further promotes the infiltration of CD4+ T cells and the expression of IFN-γ in the lungs, resulting in a more severe emphysema phenotype, although it does not significantly affect TNF-α expression." (PMID 39555065, 2024). "However, we found a higher proportion of low CD4 nadir (<200 cells per μl) and a longer duration of HIV infection in PLWH with emphysema compared to PLWH without." (PMID 33936110, 2021). "Freshly isolated CD4+T cells from PBMC of ever-smokers without (controls; n = 61) or with emphysema (n = 95) that were stimulated with lung EFs showed specific induction of IL-6, IL-17A, and IFN-γ in emphysema (right three scatter plots) as compared to controls." (PMID 22969766, 2012). "The CD4/CD8 does not solely reflect chronic immune activation and inflammation (as it can be low simply as a function of low CD4), but we have demonstrated that in the subset with HIV control and viral load suppression, the ratio remains a significant marker for emphysema." (PMID 28122034, 2017).
endometriosis (62 papers, 2010 to 2026). The growth of functional endometrial tissue in anatomic sites outside the uterine body. "Further investigation is warranted to discriminate specific CD4 + cell types involved in the affective impairment associated with endometriosis." (PMID 36311856, 2022). "IL-10 is reported to be increased in the peritoneal fluid and serum of women with endometriosis and increasing IL-10 has been linked to a decrease in CD4+ T lymphocyte activation and therefor decreased immune responses." (PMID 25207642, 2014). "Peritoneal fluid from endometriosis patients promoted Treg cell generation and inhibited Th17 cell differentiation in CD4+ T cell cultures in vitro." (PMID 40508002, 2025). "Endometriosis patients also presented an increased frequency and activation of NK, CD4+, and CD8+ cells, which interfere with embryo–endometrial dialogue." (PMID 41301684, 2025). "In detail, a meta-analysis of available public data showed that activated dendritic cells, CD4 T cells, eosinophils, and M1 macrophages were elevated in stage I–II endometriosis." (PMID 40723209, 2025). "These immune alterations are consistent with findings in reproductive disorders like endometriosis and polycystic ovary syndrome, where uterine DCs, macrophages, NK cells, and pro-inflammatory CD4+ cells are increased." (PMID 41055571, 2025). "Other estrogen-dependent diseases like endometriosis seem to also be modulated by vitamin D. Activated CD4 and CD8 cells widely express vitamin D receptors and both the activated and metabolized enzymes, 1-a-hydroxylase and 24-hydroxylase." (PMID 40868086, 2025). "The peritoneal fluid of women with endometriosis has a higher concentration of activated CD4 + T cells than that of healthy controls, suggesting an altered immune response in these patients." (PMID 40313549, 2025). "Among CD4+ T cells, a markedly increased expression of all studied TLRs was observed in the endometriosis groups (p < 0.0001 for most comparisons), with the highest levels noted for TLR3 and TLR9." (PMID 40862752, 2025). "Women with endometriosis showed a higher percentage of IL-24–producing Tregs (CD4+CD127-CD25hiFOXP3+IL-24+), IL-24–producing Tregs among CD4+ cells, and among Tregs in comparison to controls (both p < 0.05)." (PMID 40607413, 2025). "The stratification analysis suggests indeed a potential alteration in the function or phenotype of CD14+/CD16+ monocytes, CD4 CTLs, and γδt in endometriosis." (PMID 39684780, 2024). "Suppressed CD4 T cells have been reported in endometriosis due to the systemic and local alterations in immune responses." (PMID 39309679, 2024). "The equilibrium of CD4 cells in endometriosis remains contentious, with studies indicating reduced activation of both Th1 and Th2 cells in the peritoneal fluid of affected individuals." (PMID 39309679, 2024). "HOOK1 is strongly associated with M2 macrophages in endometriosis, and GBP5 is associated with a high infiltration of B-cells, CD4+ T-cells, CD8+ T-cells, and NK-cells in small cell lung cancer." (PMID 38384272, 2024). "Conversely, NK activated cells, CD4+ memory resting cells, and T follicular helper cells showed decreased infiltration in endometriosis lesions (p = 0.0279, p = 0.0032, and p = 0.0078, respectively)." (PMID 38424274, 2024). "This analysis revealed that B memory cells, CD4+ T memory cells, and T regulatory cells (Tregs) exhibited significantly higher levels of infiltration in endometriosis lesions compared to normal tissue (p = 0.00372, p = 0.0104, and p = 0.0251, respectively)." (PMID 38424274, 2024). "The authors continued experiments under Gal-9 expression in patients with endometriosis, and, using flow cytometry analysis, demonstrated the higher expression of Gal-9 on CD4+ T and Tregs cells in the PB of patients with EMS in comparison to healthy women." (PMID 38892453, 2024).
endometriosis (continued). "This study has demonstrated a notable decrease in the levels of Treg Foxp3+CD3+CD4+CD25HighCD39+CD73+ cells in the peripheral blood of women with endometriosis compared to healthy controls." (PMID 38781760, 2024). "These impaired CD4 T cells potentially contribute to the pathogenesis of endometriosis disease through cytokines, which are important for implantation and proliferation of ectopic endometrial cells, inflammation and angiogenesis." (PMID 39309679, 2024). "Another study demonstrated that CCL20 also stimulates the migration of CD4+CD25highFOXP3+ Treg cells, accelerating the progression of endometriosis." (PMID 36865552, 2023). "The concentration of T cells was higher in endometriosis lesions compared to that in eutopic endometrium, but the CD4/CD8 ratio was similar." (PMID 35628346, 2022). "Endometriosis is associated with alterations in the immune system, and high levels of CD4 + lymphocytes and macrophages have been found in the peritoneal fluid of endometriosis patients." (PMID 36311856, 2022). "Brain neuroinflammatory changes are investigated and the participation of the immune response in endometriosis-related behavioral alterations is assessed through immunological targeting of CD4 + cells." (PMID 36311856, 2022). "In endometriosis lesions, there is a lower frequency of pro-inflammatory Th1 cells, a subset of CD4+ T cells, compared to that in the eutopic endometrium." (PMID 35628346, 2022). "Patients with endometriosis with severe dysmenorrhea and acyclic pelvic pain had increased production of IL-17 by CD4+ iNKT cells and decreased numbers of CD4+ CCR7+ cells." (PMID 35576870, 2022). "Studies evaluating T cells in patients with endometriosis revealed a higher CD4/CD8 ratio and an increased concentration of each of these cell types in the peritoneal fluid of patients." (PMID 35805112, 2022). "There was an increase in the secretion of IL-17 by CD4+ iNKT cells in the blood of patients with endometriosis and severe dysmenorrhea (p = 0.038), and severe acyclic pelvic pain (p = 0.048)." (PMID 35576870, 2022). "The proportion of immune cells, including macrophages, NK cells, and CD4+Foxp3+ regulatory T cells (Tregs), is increased in the peritoneal fluid of women with endometriosis." (PMID 36310658, 2022). "In contrast, the authors also showed an increased frequency of CD4+ IL-17+ iNKT cells in patients with endometriosis with severe dysmenorrhea and with severe acyclic pelvic pain." (PMID 35576870, 2022). "When comparing the menstrual phase and iNKT subtypes, the number of CD4+ iNKT cells expressing CD25 in the proliferative phase was increased in the endometriosis group compared with the control group (44.6 vs. 33.2 [0–58.6]; p = 0.022)." (PMID 35576870, 2022). "We found different levels of immune cell infiltration and a high level in endometriosis vs. normal endometrial tissues, including CD4+ and CD8+ T cells, CD8 + Tem cells, eosinophils, monocytes, Th1 cells, memory B cells, aDCs, and pDCs." (PMID 35303800, 2022). "There was also an increased number of CD4+ iNKT cells expressing IL-17 in the peripheral blood of patients with endometriosis and severe acyclic pelvic pain compared to those with mild pain (13.1 ± 3.9 vs. 7.0 ± 5.2; p = 0.048)." (PMID 35576870, 2022). "According to Cibersort, there are abundant plasma cells, CD4+ T cells, and M2 macrophages in endometriosis." (PMID 36532015, 2022). "In our previous study, we found that the expression of CD4+ was lower in the peripheral blood of women with endometriosis compared to their counterparts." (PMID 36313261, 2022). "At the same time, a positive correlation was reported between the stage of endometriosis and the percentage of CD4+CTLA-4+ T lymphocytes and CD8+CTLA-4 T lymphocytes." (PMID 35805112, 2022).
endometriosis (continued). "The number of cells expressing CD25 was similar between the endometriosis and control groups in both the CD4+ iNKT (33.5 ± 23.1 vs. 25.8 ± 18.5; p = 0.168) and the DN iNKT subsets (39.7 ± 31.8 vs. 33.8 ± 29.8; p = 0.416)." (PMID 35576870, 2022). "Regarding T-cell subpopulations, it was demonstrated that the CD4+ T-cell profile in lesions and peripheral blood is altered in women with endometriosis." (PMID 35935991, 2022). "The number of CD4+ CCR7+ iNKT cells decreased in patients with endometriosis and severe dysmenorrhea compared to patients with mild/absent dysmenorrhea (26.9 ± 31.8 vs. 51.0 ± 21.7; p = 0.022)." (PMID 35576870, 2022). "The chemotactic activity of the peritoneal fluid of women with endometriosis for isolated CD4+ and Treg cells was significantly higher when compared to the peritoneal fluid of the control subjects." (PMID 34501240, 2021). "Here we confirmed our previous results as well as results of other investigators that the proportions of the CD4+CD25highFOXP3+ Treg cells are significantly increased in the peritoneal fluid of women with endometriosis as compared with the control group." (PMID 34501240, 2021). "At the same time, a positive correlation was demonstrated between the stage of endometriosis and the percentage of CD4+CTLA-4+ T cells and CD8+CTLA-4 T cells." (PMID 33668701, 2021). "Negative results were also observed when analyzing the productions of IFN-γ and TNF-α by CD4+ T cells in the endometriosis group compared with the control group." (PMID 34531861, 2021). "As can be seen, the proportions of the CD4+ T cells were significantly decreased in the endometriosis group compared to the control group." (PMID 34501240, 2021). "Both isolated CD4+ and Treg cells displayed significantly increased migration toward the medium containing samples of the peritoneal fluid from women with endometriosis as compared with peritoneal fluid from the control group and the medium alone." (PMID 34501240, 2021). "Taken all together, our present results provide evidence that the PF of patients with endometriosis displays immunomodulatory/immunosuppressive activities toward CD4+ T cells." (PMID 34360900, 2021). "The frequency of CD4+ T subsets were analysed by flow cytometry and com-pared between three study groups; early endometriosis (stage I, II), advanced endometriosis (stage III, IV) and control(no endometriosis)." (PMID 33098386, 2020). "Endometriosis is a complex disorder with variable immune disturbances; however, the role of CD4+ T lymphocytes deviation in different stages of disease is not completely elucidated." (PMID 33098386, 2020). "In the present study, we found a decreased CD4+ T cell number in endometriosis, which was more prominent in the PF than in the PB of the patients." (PMID 32231038, 2020). "These researchersintroduced CD4+CD25+FoxP3+ cells as Tregs andreported similar numbers of Treg cells between mild andadvanced endometriosis." (PMID 33098386, 2020). "The CD4+/PD-1 : CD4+/PD-L1+ T cell ratio was lower in the endometriosis group (1.84 ± 1.23, median 1.45, Min–Max 0.57–6.26) than in the healthy subjects (3.1 ± 1.2, median 2.83, Min–Max 3.1 ± 1.2) (p < 0.0001)." (PMID 30595667, 2018). "In line with a role for a modified immunity in the pathogenesis of endometriosis, CD4+/FoxP3+ Tregs are present in endometriotic lesions." (PMID 28902871, 2017). "One of the key regulators of immune processes in endometriosis are regulatory T cells (Tregs) derived from CD4 lineage." (PMID 28902871, 2017). "A decrease in the CD4 : CD8 ratio was observed in patients with endometriosis, which is an indication of the inhibition of the cell-mediated immune response." (PMID 25691906, 2015). "The percentage of CD4+Foxp3+ Tregs in the peritoneal fluid from women with endometriosis was furthermore highest at stage III–IV." (PMID 25275597, 2014).
endometriosis (continued). "The proportion of CD4+Foxp3+ regulatory T cells (Tregs) is significantly increased in the peritoneal fluid of women with endometriosis." (PMID 25275597, 2014). "In our study, ssGSEA revealed a correlation between endometriosis and several immune cell types, including activated CD4 + T cells, gamma-delta T cells, CD56 dim natural killer cells, eosinophils, monocytes, natural killer T cells, and plasmacytoid dendritic cells." (PMID 40313549, 2025). "Furthermore, CD4 + TLR4 in the comparison of PE vs. CC (AUC = 0.86) confirms the role of this receptor in more advanced forms of endometriosis." (PMID 40862752, 2025). "CD16+ CD4 T cell levels were significantly lower in the PB of endometriosis patients who smoke." (PMID 39337624, 2024). "For example, to identify the epigenetic changes involved in endometriosis, a genome-wide analysis of DNA methylation and enrichment of H3K4me3 and H3K27ac histone marks in sorted CD4+ and CD8+ T cells may be performed." (PMID 35935991, 2022). "The abnormal frequencies of CD4+ IL-17+ iNKT cells observed in the present study may be, in part, responsible for endometriosis-related pain symptoms." (PMID 35576870, 2022). "The authors observed a decreased number of CD4+ CCR7+ iNKT cells in patients with endometriosis and severe dysmenorrhea, suggesting that the immune response may play a role in the severity of the disease and its symptoms." (PMID 35576870, 2022). "Consequently, the CD4/CD8 ratio in blood was higher in the group of women with endometriosis compared to the control group." (PMID 35805112, 2022). "However, our data showed that the production of IFN-γ and TNF-α by CD4+ T cells in the endometriosis group were comparable with that in the control group." (PMID 34531861, 2021). "A positive correlation between the severity of endometriosis and the percentage of CD4+CTLA-4+ T cells (Spearman’s R = 0.531, p < 0.001), and a positive correlation between the severity of endometriosis and the percentage of CD8+CTLA-4+ T cells (Spearman’s R = 0.450, p = 0.001) were observed." (PMID 33668701, 2021). "In addition to the observation that the PF from women with endometriosis affects cytokine/chemokine production by CD4+ T cells." (PMID 34360900, 2021). "Half of CD4 + T cells in state 3 were from endometriosis lesions (fate 2)." (PMID 34233737, 2021). "However, we found that the proportions of both CD25lowFOXP3+ and CD25highFOXP3+ cells (Treg cells) within the CD4+ T cell population were significantly elevated in the peritoneal fluid from the endometriosis group as compared to healthy women." (PMID 34501240, 2021). "It has been reported that the proportion of CD4+CD25highFOXP3+ Treg cells may be significantly increased in the peritoneal fluid of patients with endometriosis." (PMID 34501240, 2021). "In the group of patients with endometriosis associated with infertility, a negative correlation was found between the number of CD4+CTLA-4 lymphocytes and the percentage of NK cells and the percentage of NKT-like CD3+CD16+CD56+ cells." (PMID 33668701, 2021). "Our present analysis of CD4+ T cells also revealed that their proportion may be decreased in the peritoneal fluid of women with endometriosis." (PMID 34501240, 2021). "Similarly, the inhibition of miR-342-3p regulated by lncRNA H19 reduced the percentage of T17 cells/CD4+ and T cells and inhibited endometrial stromal cell viability to relieve endometriosis." (PMID 34055578, 2021). "Moreover, in patients with endometriosis and intraoperative adhesions, significantly higher percentages of CD4+CTLA-4 and CD8+CTLA-4 T cells were observed." (PMID 33668701, 2021). "Quantitative analysis showed that the percentage of CD4+Foxp3+ Tregs was significantly increased not only in the total mononuclear cells but also in CD4+ T cells of peritoneal fluid from women with endometriosis (stage I–II and stage III–IV) compared with healthy fertile women." (PMID 25275597, 2014).